CXCR2 (C-X-C motif chemokine receptor 2)
Description:
Receptor for interleukin-8 which is a powerful neutrophil chemotactic factor. Binding of IL-8 to the receptor causes activation of neutrophils. This response is mediated via a G-protein that activates a phosphatidylinositol-calcium second messenger system. Binds to IL-8 with high affinity. Also binds with high affinity to CXCL3, GRO/MGSA and NAP-2. Involved in the homeostatic wound healing response to tissue injury, a multistep cascade that guides neutrophil migration to necrotic sites while avoiding collateral damage of healthy tissues. Signals intravascular neutrophil chemotaxis to the injury site.
Synonyms: CD182; IL8RB; CMKAR2; CDw128b; IL8R2; IL8RA; SCN13; WHIMS2
Tractability: Small molecule: a drug acting on it is in phase 2 or 3 trials; a structure with a bound ligand is known; a high-quality ligand is known; it belongs to a druggable protein family. Antibody: its Gene Ontology location is reachable by antibodies, with high confidence; UniProt places it where antibodies can reach, with medium confidence; UniProt predicts a signal peptide or a membrane-spanning region. PROTAC: a small molecule that binds it is known.
Target class: Peptide receptor (family A GPCR); Membrane receptor; Family A G protein-coupled receptor; CXC chemokine receptor; Chemokine receptor
Gene: Protein-coding gene on chromosome 2 (218,125,289 to 218,137,251, forward strand). Ensembl gene ENSG00000180871.
Subcellular location: Cell membrane
Subcellular location (Human Protein Atlas): Plasma membrane; Basal body; Microtubules; Mitotic spindle; Primary cilium; Primary cilium tip; Vesicles
Pathways (Reactome):
Signal Transduction: Chemokine receptors bind chemokines; G alpha (i) signalling events
Immune System: Neutrophil degranulation
Gene Ontology:
Molecular function: C-X-C chemokine receptor activity; G protein-coupled receptor activity; interleukin-8 binding; interleukin-8 receptor activity; protein binding; C-C chemokine binding; C-C chemokine receptor activity; chemokine receptor activity
Biological process: cell surface receptor signaling pathway; cellular defense response; chemotaxis; interleukin-8-mediated signaling pathway; neutrophil activation; neutrophil chemotaxis; phospholipase C-activating G protein-coupled receptor signaling pathway; positive regulation of cell population proliferation; receptor internalization; calcium-mediated signaling; dendritic cell chemotaxis; G protein-coupled receptor signaling pathway; immune response; inflammatory response; positive regulation of cytosolic calcium ion concentration; regulation of chemotaxis; signal transduction; chemokine-mediated signaling pathway
Cellular component: cell surface; G protein-coupled receptor complex; mast cell granule; membrane; plasma membrane; external side of plasma membrane; secretory granule membrane
Genetic constraint (gnomAD): Loss-of-function variants: 3 observed, 6.7 expected, observed/expected ratio (o/e) 0.45, 90% interval 0.2 to 1.15. That is too few expected variants to judge how well the gene tolerates losing a copy. Missense variants: 351 observed, 466.02 expected, observed/expected ratio (o/e) 0.75, 90% interval 0.69 to 0.82. Synonymous variants: 203 observed, 199.42 expected, observed/expected ratio (o/e) 1.02, 90% interval 0.91 to 1.14.
Homologues: Orthologues: chimpanzee CXCR2 (100% identical), macaque CXCR2 (90% identical), rabbit CXCR2 (81% identical), dog CXCR2 (75% identical), guinea pig CXCR2 (73% identical), mouse Cxcr2 (71% identical), rat Cxcr2 (70% identical), tropical clawed frog cxcr2 (56% identical), zebrafish cxcr2 (41% identical). Paralogues in human: CXCR1 (75% identical), CXCR3 (38% identical), CCR6 (36% identical), CXCR5 (36% identical), CCR4 (34% identical), CCR7 (33% identical), CXCR4 (33% identical), CCR9 (33% identical), ACKR2 (32% identical), ACKR4 (31% identical), CCR1 (30% identical), CCR8 (30% identical), and 11 more.
Diseases named in the same sentence as CXCR2 in open-access papers:
CXCR2 is named in the same sentence as 410 diseases in open-access papers, as found by Europe PMC text mining. Sharing a sentence is not in itself a finding about the gene and the disease. The quoted sentences say what the papers report.
breast cancer (171 papers, 2010 to 2026). A primary or metastatic malignant neoplasm involving the breast. "High CXCR2 expression has been associated with poor prognosis in various cancers, including acute myeloid leukemia, breast cancer, and ovarian cancer, due to its role in promoting tumor cell proliferation and metastasis." (PMID 40867594, 2025). "Clinical data analysis showed that poor PFS was correlated with high expression of CXCR2 in breast cancer patients, and CXCR2 was an independent risk factor determining breast cancer prognosis." (PMID 39394189, 2024). "Conversely, deficiency of CXCR2 inhibited neutrophil infiltration in murine breast cancer models and inhibited the occurrence of metastases." (PMID 37158964, 2023). "KDM2A-expressing CAFs dominantly secreted the CXCR2-associated chemokines to promote M2 macrophage polarization and enhance paclitaxel resistance in breast cancer." (PMID 37821959, 2023). "Our results identify CXCR2 activation as a major regulator of not only the recruitment of Tumor-Associated Neutrophils toward brain metastatic variants of breast cancers, but also their propensity of NETosis with unique tumor-aiding spatio-temporal dynamics." (PMID 35158784, 2022). "In this paper, we have shown that CXCR2 in neutrophils is upregulated in response to the overexpression of the corresponding ligands in brain metastatic variants of breast cancers." (PMID 35158784, 2022). "We have recently shown that CXCR2 was expressed by neutrophils in breast cancer samples and that CXCR2 was associated with a lower risk of relapse in patients." (PMID 34070438, 2021). "MSCs activated by IL-1β secrete other inflammatory cytokines, such as CXCL1, which is implicated through signaling through CXCR2 expressed on breast cancer cells in the dissemination, poor patient prognosis, chemo-resistance, and metastasis." (PMID 29262555, 2017). "Based on the abundant evidence for the role of IL-8 and CXCR2 in carcinogenesis, we evaluated in this study the association of CXCR2 (+ 1208) C/T gene polymorphism and breast cancer susceptibility and prognosis in Tunisia." (PMID 20540789, 2010). "The CXCR2 (+ 1208) T allele manifested a significant association with an aggressive phenotype of breast carcinoma as defined by a large tumor size, a high histological grade, and auxiliary's lymph node metastasis." (PMID 20540789, 2010). "More interestingly, we showed that IL-8 (-251) A and CXCR2 (+1208) T alleles were associated with a shorter overall survival and disease-free survival and, therefore, with a poor prognosis in breast carcinoma." (PMID 20540789, 2010). "The presence of two higher risk genotypes (the TA and TT in IL-8, and the TT in CXCR2) significantly increased the risk of developing breast carcinoma (adjusted OR = 4.15; P = 0.0004)." (PMID 20540789, 2010). "Given the importance of IL-8 and CXCR2 in angiogenesis, we investigated the relationship between polymorphisms -251 T/A in IL-8 gene and (+1208) C/T in CXCR2 gene and breast carcinoma." (PMID 20540789, 2010). "Because IL-8 functionally interacts with CXCR2 we assessed the effect of multiple genotypes on breast carcinoma risk." (PMID 20540789, 2010). "Taken together, these results suggest that the (-251) A allele of the IL-8 gene and the (+1208) T allele of the CXCR2 gene are associated with the aggressive forms of breast carcinoma." (PMID 20540789, 2010). "The estimated 3- and 6-year breast carcinoma OVS rate in the group of patients carrying CXCR2 (+1208) T allele were, respectively, 87.1 and 65.7% versus 95.7% and 90% for those not carrying the (+1208) T allele (log rank test, P < 0.001)." (PMID 20540789, 2010). "A highly significant association was found between the homozygous CXCR2 (+ 1208) TT genotype (adjusted OR = 2.89; P = 0.008) and breast carcinoma." (PMID 20540789, 2010). "In summary, our data suggests that IL-8 (-251) T/A and CXCR2 (+1208) C/T polymorphisms are likely to play a major role in susceptibility to and prognosis in breast carcinoma." (PMID 20540789, 2010).
breast cancer (continued). "Evidence from both in vitro and in vivo experiments indicates that senkyunolide H may exert its therapeutic effect by regulating CXCR2, thereby counteracting the protumor effects associated with depression in breast cancer." (PMID 40839237, 2025). "However, recent data suggests that one of the mechanisms inducing chemoresistance and progression in breast cancer is driven by chemokine receptor CXCR2 overexpression, causing Akt1 suppression and COX2 activation." (PMID 31921382, 2019). "Inhibited myeloid cell infiltration due to the loss of CXCR2 was also shown to be responsible for suppressed chronic colonic inflammation, colitis-associated tumorigenesis and reduction of metastasis in murine breast cancer tumor model." (PMID 29340117, 2017). "VEGF-D has been linked to the CXCL7/CXCR2 axis and tumor cell invasion in a study on breast cancer." (PMID 24502459, 2014). "Furthermore, this study provides support for the multigenetic effects of the variant alleles from IL-8, and CXCR2, resulting in a significantly increased risk for breast cancer in the Tunisian population." (PMID 20540789, 2010). "Finally, we combined the IL-8 and CXCR2 variant alleles and analyzed their effects in breast cancer risk and prognosis." (PMID 20540789, 2010). "Although additional studies on a larger scale will be required to confirm and extend our findings, the present data suggest for the first time that CXCR2 (+1208) C/T polymorphism represents a risk factor for poorer prognosis and susceptibility to breast carcinoma." (PMID 20540789, 2010). "Using the IL-8 (-251) T/A and CXCR2 (+1208) C/T polymorphisms alone or in combination with other genetic polymorphisms in angiogenic and inflammatory genes to predict breast carcinoma outcome and prognosis may therefore have an important clinical significance." (PMID 20540789, 2010). "Moreover, the presence of the IL-8 (-251) A and/or the CXCR2 (+ 1208) T allele showed a significant association with a decreased overall survival and disease-free survival in breast carcinoma patients." (PMID 20540789, 2010). "Our current study aims to confirm these results in a larger cohort and to determine whether there is any association between the genetic polymorphism of the CXCR2 and both individual susceptibility to and prognosis of breast carcinoma." (PMID 20540789, 2010). "Therefore, targeted intervention with CXCR2 may be more effective against breast cancer associated with depression." (PMID 40839237, 2025). "We also constructed Cxcr2- and Cfb-knockout (Cxcr2–/– and Cfb–/–) mice and implanted mouse breast cancer cells into the fourth fat pads, followed by Dox administration." (PMID 41480760, 2026). "Inhibition of CXCR2 signaling suppressed the metastatic ability of colorectal, hepatocellular, and breast cancer cells." (PMID 41155662, 2025). "By studying these two receptors, we further confirmed that CXCR2 activation can significantly promote breast cancer growth." (PMID 40839237, 2025). "In breast cancer, the IL-8/ CXCR2 axis inhibition by SB225002 also proves its high effectiveness in preventing tumor growth and metastasis." (PMID 41155662, 2025). "Cancer-associated fibroblasts (CAFs) also contribute to the network by promoting TAM recruitment through the CXCL12/CXCR4 axis in breast cancer (BC) and the IL-8/CXCR2 axis in colorectal cancer (CRC)." (PMID 41417432, 2025). "The results revealed that IL-8 significantly promoted breast cancer cell proliferation, whereas CXCR2 knockdown significantly reversed the promoting effect of IL-8 on the growth of breast cancer cells." (PMID 40839237, 2025). "While CXCL1 is highly expressed in several triple negative breast cancer cell lines, CXCR2 expression is reported to be reduced compared to other breast cancer subtypes." (PMID 40108668, 2025). "For example, the use of a CXCR2 inhibitor or anti-IL-8 antibody in breast cancer models reduced neutrophil infiltration and metastatic seeding in distant organs." (PMID 41007766, 2025).
breast cancer (continued). "Further studies demonstrated that IL-8 mediated the breast cancer-promoting effect of depression through the receptor CXCR2." (PMID 40839237, 2025). "The potential of blocking neutrophil recruitment pathways, such as the CXCR2 axis, in the treatment of aggressive breast cancers like TNBC is an area of active research." (PMID 40734715, 2025). "CAFs exposed to neoadjuvant chemotherapy secrete chemokines like Glu-Leu-Arg (ELR) motif-positive chemokines, enhancing breast cancer cell invasion through CXCR2." (PMID 40230452, 2025). "Despite the lack of IL-8 in mice, depression can still promote the growth of breast cancer through CXCR2." (PMID 40839237, 2025). "In mouse breast cancer xenografts, CXCR2 knockdown allowed paclitaxel-treated animals to develop stronger anti-cancer activity and fewer lung metastases." (PMID 39394189, 2024). "It was discovered that breast cancer cells that survived chemotherapy and radiation therapy expressed higher levels of CXCR2." (PMID 39394189, 2024). "TAM-derived CXCL8 promotes breast cancer stem cell (BCSC) self-renewal and elevates breast cancer metastasis, and the CXCR2 antagonist danirixin inhibits the TAM/CXCL8 regulatory mechanism to eliminate BCSCs." (PMID 39199574, 2024). "Inhibition of CXCR2, either by knockdown or by transplanting CXCR2-deficient MDSCs, significantly reduced stress-induced MDSC accumulation, NET formation, and breast cancer metastasis." (PMID 39090094, 2024). "In a mouse model of breast cancer, MDSCs features included several genes related to immunomodulation, such as arginase 2 and Cd84, and chemokine receptors (e.g., Ccr2 and Cxcr2), suggesting that MDSCs can be directed into tumor tissue by chemokines." (PMID 38609997, 2024). "By binding to its receptors, CXCR1 and CXCR2, IL-8 supports breast cancer progression by promoting tumor cell invasion and metastases." (PMID 37762330, 2023). "The simultaneous expression of CXCL1 and the receptor for this chemokine, CXCR2, allows breast cancer stem cells to act on themselves in an autocrine manner." (PMID 37108425, 2023). "After binding to its receptor CXCR2, CXCL1 activates many pathways implicated in breast cancer including phosphatidylinositol-4,5-bisphosphate 3-kinase-γ (PI3Kγ)/Akt, MAP kinases such as ERK1/ERK2 or phospholipase-β (PLCβ) signaling pathways." (PMID 38022682, 2023). "4T1 breast cancer cells were then orthotopically inoculated at the sixth week, followed by intrasplenic injection of mCherry-labeled CXCR2+/+ or CXCR2−/− MDSCs." (PMID 37210553, 2023). "CXCR2 knockdown in breast cancer cells diminished the PMN-MDSC-induced enhancement of breast cancer cell stemness." (PMID 36859354, 2023). "CCL20-modulated PMN-MDSCs secreted amounts of CXCL2 and activated NOTCH1/HEY1 signaling pathway in breast cancer cells by binding to CXCR2, leading to the increase of ALDH+ BCSCs." (PMID 36859354, 2023). "CXCR2 expression in breast tumors is mainly found in cancer stem cells, and for this reason, CXCR2 can be considered a marker of breast cancer stem cells." (PMID 37108425, 2023). "Collectively, these results suggest that CXCR2-associated chemokines released from K2A-1 promote M2 macrophage polarization, which in turn secretes CCL2 to increase the resistance of breast cancer cells to paclitaxel." (PMID 37821959, 2023). "The expression of the receptor for CXCL1, i.e., CXCR2, is lower in triple-negative breast cancer compared to other breast cancer subtypes." (PMID 37108425, 2023). "Once cancer cells metastasize to the bone, different chemokine motif ligands (CXCL12, CXCR4, CXCL5, CXCR2) promote breast cancer cell colonization within the bone." (PMID 36674719, 2023). "Previous data showed that knockdown of CXCR2 enhances doxorubicin-mediated toxicity in mammary tumor cells." (PMID 35517812, 2022). "Apart from CXCR1, CXCR2 has been shown to modulate the development, progression and drug response of breast cancer." (PMID 35054486, 2022).